CTAGE4 (CTAGE family member 4)
Description:
Tumor-associated antigen.
Synonyms: FLJ43692; cTAGE-4
Tractability: Antibody: UniProt predicts a signal peptide or a membrane-spanning region.
Gene: Protein-coding gene on chromosome 7 (144,183,466 to 144,186,080, forward strand). Ensembl gene ENSG00000288784.
Subcellular location: Membrane
Gene Ontology:
Biological process: endoplasmic reticulum to Golgi vesicle-mediated transport; protein secretion; vesicle cargo loading
Cellular component: endoplasmic reticulum exit site; endoplasmic reticulum membrane; membrane
Genetic constraint (gnomAD): Missense variants: 11 observed, 81.33 expected, observed/expected ratio (o/e) 0.14, 90% interval 0.084 to 0.22. Synonymous variants: 2 observed, 27.93 expected, observed/expected ratio (o/e) 0.0716, 90% interval 0.028 to 0.22.
Homologues: Orthologues: dog MIA2 (76% identical), mouse Mia2 (68% identical), rat Mia2 (68% identical), Drosophila melanogaster Tango1 (21% identical). Paralogues in human: CTAGE8 (99% identical), CTAGE9 (99% identical), CTAGE15 (97% identical), CTAGE6 (96% identical), MIA2 (83% identical), CTAGE1 (75% identical), MIA3 (27% identical), SPZ1 (8% identical), MIA (2% identical), OTOR (1% identical).
Diseases named in the same sentence as CTAGE4 in open-access papers:
CTAGE4 is named in the same sentence as 1 disease in open-access papers, as found by Europe PMC text mining. Sharing a sentence is not in itself a finding about the gene and the disease. The quoted sentences say what the papers report.
cutaneous T-cell lymphoma (1 paper, 2025). "CTAGE4, initially described as a tumor-associated antigen in cutaneous T-cell lymphoma, may be significant in the context of clonal T-cell proliferation." (PMID 41488087, 2025).